IL6 (interleukin 6)
Diseases named in the same sentence as IL6 in open-access papers (continued):
Sharing a sentence is not in itself a finding about the gene and the disease.
brucellosis (24 papers, 2007 to 2026). Brucellosis is a bacterial infection that spreads from animals to people via unpasteurized dairy products or by exposure to contaminated animal products or infected animals. "Previous studies have explored the association of IL-10 and IL-6 polymorphisms with Brucellosis risk." (PMID 32228609, 2020). "We found that the expression of all six cytokines tested was closely related to the degree of brucellosis using univariate logistic regression; however, only IL-6 and INF-γ levels were independent factors associated with the severity of brucellosis." (PMID 32381058, 2020). "IL-10 (− 1082 G/A, − 819 C/T, − 592C/A) and IL-6 -174 G/C polymorphisms have a great relationship with IL-10 and IL-6 production, which brings about Brucellosis pathogenesis and development." (PMID 32228609, 2020). "Whereas carrying +874 AA genotype in IFN-γ, producing high/medium IL-10 genotypes, and producing high IL-6 genotype are associated with susceptibility to brucellosis." (PMID 31582997, 2019). "Further evaluation of both the role of this IL-6 genetic variant and the function of IL-6 in brucellosis is required." (PMID 29343543, 2018). "IL-17A has been associated with chronic pain, similar to IL-6, and might explain the presence of pain in acute and chronic brucellosis." (PMID 38794208, 2024). "The IL-6 (-174) GC genotype may be a risk factor for the development of focal complications of brucellosis, whereas the GG genotype may be a protective factor against brucellosis." (PMID 34306007, 2021). "In this study, we examined the relationship between brucellosis and cytokine levels, and found IL-4, IL-6, IL-10, IL-17, IFN-γ, and TNF-α were all risk factors for brucellosis, although only IL-6 and INF-γ were independent risk factors for the severity of brucellosis." (PMID 32381058, 2020). "Other pro-inflammatory cytokines essential in controlling brucellosis include IL-6, IFN-γ, and TNF-α." (PMID 40589729, 2025). "The results indicated that the levels of IL-6 and Arg-1 were elevated in the serum of brucellosis infected patients, with CBI group exhibiting higher levels than ABI group (P<0.01, P<0.001)." (PMID 41234517, 2025). "Comparable findings have been reported in human patients with brucellosis, where monocytes exhibited diminished IL-1β, IL-6, and IL-10 secretion in response to LPS stimulation." (PMID 40406273, 2025). "Significantly higher levels of TNF-α, IFN-α, and IL-6 also distinguished SLAMFhi from SLAMFlo brucellosis patients." (PMID 40231463, 2025). "The concentration of several inflammatory mediators was measured in the serum of these patients, and levels of IFN-γ, IL-1β and IL-6 were found significantly increased before the treatment of acute brucellosis." (PMID 35979363, 2022). "In the multivariate logistic stepwise regression analysis, IL-6 and INF-γ were found to be independent risk factors for brucellosis after adjusting for age and gender." (PMID 32381058, 2020). "With regards to the degree of infection (as assessed by brucellosis antibody titer), we found only IL-6 levels were altered." (PMID 32381058, 2020). "In our univariate analysis, IL-4, IL-6, IL-10, IL-17, IFN-γ, and TNF-α were risk factors for brucellosis." (PMID 32381058, 2020). "Corroborating previous studies, we showed here that Brucella induces IL-6 secretion, and it was recently shown that patients with brucellosis exhibit higher IL-6 levels compared to control patients." (PMID 33322581, 2020). "Taken together, these data show IL-6 acting as an important regulator of immunity during brucellosis, and imply that IL-6 is a promising therapeutic target during bacterial infections." (PMID 33322581, 2020). "Conversely, 3-MA treatment that inhibited autophagy led to elevated expression of TNF-α, IL-6, IL-1β, and IL-10 than those from untreated monocytes from brucellosis patients." (PMID 28659924, 2017).
brucellosis (continued). "Overall, our data suggest that IFN-γ, IP-10, IL-1a, IL-1ß, IL-6 could enhance brucellosis diagnosis in Mediterranean Buffaloes." (PMID 40406273, 2025). "Notably, the chronic form of bovine brucellosis was associated with increased expression of IFN-γ, IL-1β, IL-6 and iNOS genes, along with reduced expression of TNF-α, IL-4 and IL-12p40 genes." (PMID 39825331, 2025). "Similarly, we observed that Mediterranean Buffaloes with brucellosis release lower levels of three pro-inflammatory cytokines than healthy controls: IL-1α, IL-1β, IL-6." (PMID 40406273, 2025). "From the initial 15, we narrowed it down to five: our analysis showed that the quantitative determination of IFN-γ, in parallel with the chemokine IP-10 and three pro-inflammatory cytokines (IL-6, IL-1α and IL-1β) could be useful in the diagnosis of brucellosis in Mediterranean Buffaloes." (PMID 40406273, 2025). "And other polymorphisms of IL-10 and IL-6 are not related with Brucellosis susceptibility." (PMID 32228609, 2020). "We found that IL-4, IL-6, IL-10, IL-17, IFN-γ, and TNF-α levels were higher in those with brucellosis than in controls." (PMID 32381058, 2020). "We investigated changes in the levels of six cytokines (IL-4, IL-6, IL-10, IL-17, TNF-α, INF-γ) and related clinical biochemical markers in patients with acute and chronic brucellosis in Xinjiang, China." (PMID 32381058, 2020). "We found that IL-4, IL-6, IL-10, IL-17, IFN-γ, and TNF-α levels were higher in those with brucellosis than in controls (P < 0.05)." (PMID 32381058, 2020). "Levels of IL-4, IL-6, IL-10, IL-17, IFN-γ, and TNF-α were all significantly higher in those with brucellosis than in the control group (all P < 0.05)." (PMID 32381058, 2020). "We found that IL-4, IL-6, IL-10, IL-17, IFN-γ, and TNF-α levels were higher in patients with brucellosis than healthy controls, indicating a strong immune response was occurring." (PMID 32381058, 2020). "Additionally, we also detected high expression of typical inflammatory cytokines (e.g., S100A8/9/12, IL1B, IL6, CXCL8, CCL2, CXCL10) in brucellosis patients during the acute phase." (PMID 39135683, 2024). "In vivo, IL-6, TNF-α, and CD80/CD86 are required for activation of the interferon gamma-producing CD4+ Th1 and CD8+ cytotoxic T cells, a protective response induced by the host against brucellosis." (PMID 34992597, 2021). "In vivo, IL-6, TNF-α, and CD80/CD86 are required in the activation of the interferon gamma-producing T CD4+ helper type 1 (Th1) and T CD8+ cytotoxic, a protective response induced by the host against brucellosis." (PMID 32765455, 2020). "In particular, we propose IL-6 and INF-γ may be useful independent predictive factors in the clinical evaluation and diagnosis of brucellosis." (PMID 32381058, 2020). "In particular, we propose IL-6 and INF-γ levels may be useful independent predictive factors in the clinical evaluation and diagnosis of brucellosis." (PMID 32381058, 2020). "Although the function of IL-6 in brucellosis is not clear, previous studies showed a significant association between an IL-6 polymorphism and brucellosis patients in Turkey." (PMID 29343543, 2018). "Additionally, the production of IL-1β, IL-6, IL-10, and TNF-α from monocytes in patients with brucellosis was suppressed through the LC3-dependent autophagy pathway during Brucella infection." (PMID 28659924, 2017). "In the acute phase of brucellosis, infected patients exhibit higher levels of cytokines, such as TNF-α, IL-6 or IFN-γ, and IL-10, compared to Brucella-negative individuals." (PMID 38139181, 2023). "It is also significant that the ability of macrophages to control intracellular B. abortus is affected by IL-10 only at very high concentrations, and that IL-6 and TNF-α have no major effect, in contrast to INF-γ which is the key cytokine in the control of brucellosis." (PMID 17637846, 2007).
colorectal adenoma (24 papers, 2010 to 2025). An adenoma that arises from the colon or rectum. "In contrast to our results, certain studies suggested that higher levels of IL-6 in the serum are linked to the existence of colorectal adenoma." (PMID 39439893, 2024). "Circulating IL-6 levels was found associated with the risk of colorectal adenomas among subjects with homeostasis model assessment of insulin resistance≥1.73, but not among those<1.73." (PMID 27608842, 2016). "Prior studies from our group demonstrated that increased systemic levels of pro-inflammatory cytokines IL-6 and TNFα correlate with risk of colorectal adenoma." (PMID 20500855, 2010). "Previous research from our group has shown that increased levels of circulating, pro-inflammatory cytokines IL-6 and TNFα promote colorectal adenoma risk." (PMID 20500855, 2010). "Consistent with our findings, one study of colorectal adenoma reported that the use of NSAIDs was positively associated with high levels of other inflammatory proteins, IL‐6 and TNF‐alpha, which the authors concluded could be due to confounding by indication." (PMID 39482824, 2025). "The pooled results on CRP and IL-6 and risk of colorectal adenomas are consistent with those from nested case-control studies in which circulating levels measurement preceded colorectal adenomas incidence." (PMID 27608842, 2016). "The IL-6 expression level elevates gradually during the progression from colorectal adenoma to carcinoma." (PMID 40149674, 2025). "The serum levels of IL-6 increase during the progression from colorectal adenoma to carcinoma, and, consistently, CAC and CRC patients with high serum levels of IL-6 present with tumors of large size, relapse, and shorter overall survival." (PMID 40722631, 2025). "Based on these facts, it is important in the clinical setting to screen colorectal adenomas in CRC patients with a high postoperative level of IL-6." (PMID 37194025, 2023). "Previously published results on colorectal adenomas found that a high abundance of F. nucleatum was positively correlated with the expression of inflammatory cytokine genes, such as IL-6 and TNF-α, which is similar to our findings." (PMID 38075864, 2023). "For highest vs. lowest levels, results from this meta-analysis did not support an association between circulating levels of CRP [OR (95% CI): 1.15 (0.94-1.40)], IL-6 [1.17 (0.94-1.46)] and TNF-α [0.99 (0.75-1.31)] and risk of colorectal adenomas, respectively." (PMID 27608842, 2016). "Previous studies regarding associations between IL-6 and TNF-α levels and colorectal adenomas are inconsistent." (PMID 24235998, 2013). "Several studies on colorectal adenomas have also demonstrated a positive correlation between elevated Fusobacterium nucleatum levels and increased expression of inflammatory cytokines, including IL-6 and TNF-α." (PMID 41267807, 2025). "In conclusion, serum IL-6 amount and autophagic markers could be good predictors of the presence of colorectal adenomas." (PMID 35563601, 2022). "The IL-6 expression level is gradually elevated during the progression from colorectal adenoma to carcinoma, but no clear correlation between IL-6 concentration and risk of polyp number or its type was found." (PMID 35884974, 2022). "The F. varium-stimulated DC line produced high levels of IL-6, IL-8, or TNF-α, consistent with our previous report indicating that F. varium in actively inflamed colonic mucosa was associated with the progression of UC36 and the pathogenesis of colorectal adenoma and intramucosal CRC25." (PMID 35739324, 2022). "The levels of inflammatory biomarkers in both blood (i.e., IL-6, IL-8, IgA, IgM, and IgG) and fecal samples (i.e., FCP) were evaluated in 97 colorectal adenoma patients who had blood samples available." (PMID 37686736, 2023).
colorectal adenoma (continued). "Some RCTs have indicated significant favorable effects of vitamin D supplementation on inflammatory cytokines such as IL-6, sTNF-R2, and CRP, but only in precisely chosen groups of diabetics patient and patients with colorectal adenoma." (PMID 31350967, 2019). "Results from publications on inflammatory markers of C-reactive protein (CRP), interleukin-6 (IL-6) and tumor necrosis factor-α (TNF-α) and risk of colorectal adenomas are not consistent." (PMID 27608842, 2016). "The departure from a linear relationship was not significant between CRP (Pfor nonlinearity=0.18), IL-6 (Pfor nonlinearity=0.35) and TNF-α (Pfor nonlinearity=0.87) and risk of colorectal adenoma, respectively." (PMID 27608842, 2016). "Recent evidence indicates that serum levels of IL-6 and TNF-α may be elevated in those with colorectal adenoma." (PMID 24235998, 2013). "IL-6 and TNF-α have been associated with colorectal adenoma in a few studies but not in others." (PMID 24235998, 2013). "Decreased IL-6 secretion might correlate with CRC regression or blockage of tumor formation, as the change of the cytokine profile in the colon even at early time points might create the formation of an anti-tumorigenic microenvironment thus restricting the colorectal adenoma-carcinoma development." (PMID 28881611, 2017). "Circulation levels of CRP, IL-6 and TNF-α might be not useful biomarkers for identifying colorectal adenomas, respectively." (PMID 27608842, 2016). "In summary, circulating levels of CRP, IL-6 and TNF-α may be not useful biomarkers for identifying colorectal adenomas." (PMID 27608842, 2016).
eczema (24 papers, 2006 to 2026). "In one of the studies, the children with eczema had higher IL-6 and IgE levels, and after Vitamin D supplementation, both IgE and pro-inflammatory IL-6 were reduced to near-normal levels." (PMID 37239112, 2023). "Additional features include eczema, impaired inflammatory responses during infection, increased serum IgE and IL-6." (PMID 38835414, 2023). "Some studies also found that the abundance of Ruminococcaceae decreased in infants with eczema, and inflammatory cytokines such as IL-6 and TNF-α increased, and a decrease in the number of Ruminococcus can induce a toll-like receptor inflammatory response." (PMID 36710970, 2022). "Scratching but not doctors diagnosed eczema was associated with higher levels of maternal IL-5, IL-6, and IL-13 during pregnancy." (PMID 27222655, 2016). "We report that scratching behavior but not doctors diagnosed eczema among infants was associated with higher levels of maternal serum but not breast milk IL-5, IL-6, and IL-13 cytokines." (PMID 27222655, 2016). "The serum levels of IL-6, IL-17, and TNF-α are also downregulated through the downregulation of mitogen-activated protein kinase (MAPK) and the NF-κB pathway by treatment with MC-EO in a DNCB-induced eczema mouse model." (PMID 38791435, 2024). "ELISA and Western blotting analyses revealed that SYXL alleviated eczema-like skin lesions induced by DNCB in animal models, reversed histopathological abnormalities, curbed the expression of pro-inflammatory cytokines IL-1β, IL-6, and TNF-α, and inhibited the phosphorylation of JAK2 and STAT3." (PMID 40612058, 2025). "Thus, impaired IL-6 signaling may contribute to the Th2-skewed immune profile reported in WAS patients and may be particularly relevant to the pathogenesis of eczema." (PMID 41035657, 2025).
essential hypertension (24 papers, 2007 to 2026). Hypertension that presents without an identifiable cause. "Clinical data demonstrated that inflammatory biomarkers such as CRP, IL-6, and TNF-α significantly increased in primary hypertension, and this increase is observed significantly more often in nondippers and is associated with the onset of target organ damage and cardiovascular events." (PMID 28757677, 2017).
hemophagocytic lymphohistiocytosis (24 papers, 2004 to 2025). "Proinflammatory cytokines in the IL-1 family are regulators of IL-6 production, and high levels of IL-1β have been associated with cytokine storms and hemophagocytic lymphohistiocytosis." (PMID 36936774, 2023). "For example, IL-1β has been reported to be associated with systemic symptoms such as fever; IL-6, with arthritis and typical skin rash; and IL-18, with hemophagocytic syndrome and liver injury." (PMID 36494453, 2022). "Extremely elevated IL-6 concentrations have also been observed in specific clinical contexts, such as pediatric hemophagocytic lymphohistiocytosis secondary to melioidosis (IL-6 > 1400 pg/mL)." (PMID 41439926, 2025). "There is also evidence of an increase in IL-6 and IL-1β secretion in EBV-associated diseases, such as infectious mononucleosis and hemophagocytic lymphohistiocytosis." (PMID 36675141, 2023). "Trend of change in cytokine levels (IL-10, IFN-γ, IL-6) (pg/mL), neutrophil count (×109/L), hemoglobin level (g/L), and platelet count (×109/L) since the onset of hemophagocytic lymphohistiocytosis." (PMID 34964741, 2021). "Excessive activation of monocytes attributable to stimulation by high levels of Th1 cytokines, such as interferon-γ, tumor necrosis factor-α, interleukin (IL)-1 or IL-6, are proposed as possible immunopathologic mechanism of hemophagocytic lymphohistiocytosis." (PMID 15496237, 2004). "Persistently elevated IFN-γ, IL-6, and IL-10 in non-survivors also raised the possibility of an association with hemophagocytic lymphohistiocytosis (HLH)." (PMID 39931580, 2024). "Other cytokine sources during COVID-19 infection are through pyroptosis (IL6, IL1α, IL1β), hemophagocytic lymphohistiocytosis (IFNγ, IL2), and angiotensin II viral mimicking (IL6 positive feedback loop)." (PMID 33921113, 2021). "We present a case of hematological toxicity, manifested as hemophagocytic syndrome (HPS), which was successfully treated with an anti-interleukin-6 antibody (tocilizumab)." (PMID 33628551, 2021).